OTX2-AS1 (OTX2 antisense RNA 1)
Synonyms: OTX2OS1
Gene: Long non-coding RNA gene on chromosome 14 (56,813,183 to 57,152,177, forward strand). Ensembl gene ENSG00000248550.
Diseases named in the same sentence as OTX2-AS1 in open-access papers:
OTX2-AS1 is named in the same sentence as 2 diseases in open-access papers, as found by Europe PMC text mining. Sharing a sentence is not in itself a finding about the gene and the disease. The quoted sentences say what the papers report.
medulloblastoma (1 paper, 2023). A malignant, invasive embryonal neoplasm arising from the cerebellum. "Our study revealed a pro-tumorigenic role of OTX2-AS1 in medulloblastoma and identified BCL-2 inhibition as a potential therapeutic approach to target OTX2-AS1 overexpressing medulloblastoma cells." (PMID 37976029, 2023). "To determine genetic alterations and expression of OTX2-AS1 in medulloblastoma, we comprehensively analyzed DNA copy number alterations targeting the OTX2-AS1 gene locus and OTX2-AS1 expression levels in published data sets." (PMID 37976029, 2023). "OTX2-AS1 knockout reduced medulloblastoma cell viability and cell migration in vitro and prolonged survival in the D283 orthotopic medulloblastoma mouse xenograft model." (PMID 37976029, 2023). "To study whether OTX2-AS1 may modulate the migration of medulloblastoma cells, we performed real-time cell analyses and continuously monitored cell migration in the different OTX2-AS1 engineered cell models." (PMID 37976029, 2023). "In addition, we provide evidence that hypermethylation of the OTX2/OTX2-AS1 promoter is common in SHH medulloblastoma and may thereby result in low expression levels of the OTX2 and OTX2-AS1 transcripts in this medulloblastoma group." (PMID 37976029, 2023). "In addition, OTX2-AS1 expression may serve as a molecular biomarker to indicate the vulnerability of medulloblastoma cells toward pharmacological inhibition of BCL-2." (PMID 37976029, 2023). "Therefore, our findings indicate that the upregulation of OTX2-AS1 expression in medulloblastoma is associated with an increase in OTX2-AS1 copy number and the absence of OTX2/OTX2-AS1 promoter methylation." (PMID 37976029, 2023).
OTX2-AS1 also shares sentences with these, for which no sentence is quoted: mastocytosis (1 paper).